MBP (myelin basic protein)
Diseases named in the same sentence as MBP in open-access papers (continued):
Sharing a sentence is not in itself a finding about the gene and the disease.
Stroke (continued). "IL-4-deficient mice displayed exacerbation of the loss in MBP and a further increase in the SMI32/MBP ratio compared to WT mice, suggesting that IL-4 is important in maintaining axonal myelination or promoting axonal remyelination after stroke." (PMID 31226122, 2019). "Moreover, linagliptin treatment after stroke decreased the presence of peptides derived from neurogranin and from an isoform of the myelin basic protein." (PMID 29776406, 2018). "In a study with 40 patients, anti-MBP antibody titers were associated with cognitive decline during the first year after stroke, but we still do not completely understand the pathological consequences of this humoral response." (PMID 29422904, 2018). "A powerful immune response toward MBP was triggered by Th1 lymphocytes following an IS and was demonstrated to correlate with a poor clinical outcome at 90 days, even when adjusted for National Institute of Health Stroke Scale (NIHSS) score and age." (PMID 27898011, 2016). "However, immune tolerance to myelin basic protein prior to stroke improved functional recovery in mice." (PMID 24485041, 2014). "Systemic inflammation at the time of experimental stroke has been used experimentally to mimic the clinical situation of infection to increase the likelihood of developing a detrimental autoimmune response to brain antigens by favoring Th1 responses to MBP." (PMID 25309322, 2014). "Nevertheless, the tendency to develop a Th1 response to MBP could be increased by lipopolysaccharide (LPS)-mediated induction of a systemic inflammatory response at the onset of the stroke." (PMID 25539803, 2014). "The results revealed significant negative correlations between MBP intensity and the latency to touch and remove the adhesive tape at 35 d after stroke, confirming an association between histological observations of white matter integrity and long-term functional recovery of behavioral endpoints." (PMID 31226122, 2019). "Additionally, immune responses against myelin basic protein (MBP) and glial fibrillary acidic protein (GFAP) have been associated with larger cerebral infarctions and increased the likelihood of worse outcome in stroke patients." (PMID 26742037, 2016). "BBB abnormality is generally more diffuse in small vessel stroke compared to non-lacunar stroke subtypes that may cause gradual and sustained leakage of brain-specific MBP into general circulation." (PMID 24752076, 2014). "Meanwhile, LIPUS-treated mice had significantly higher MBP and SMI32 staining area ratios on day 28 after stroke compared with dMCAO group mice." (PMID 40290135, 2025). "The importance of these mechanisms in stroke was elucidated through experiments that inhibit or eliminate the expression of DNMT, TET, and MBP." (PMID 36142283, 2022). "Recent studies demonstrate the presence of MBP-and PLP-autoantibodies in patients with stroke, where more than 50% of all survivors suffer from dysphagia." (PMID 33810144, 2021). "Twenty‐eight days after stroke, demyelination and massive exposure of non‐phosphorylated neurofilaments, as well as an increased SMI32/myelin basic protein (MBP) immunofluorescence ratio were observed." (PMID 33650762, 2021). "To test the effects of delayed VT treatment on white matter integrity after stroke in T1DM rats, we employed BS, LFB, and MBP staining as well as SMI‐32 and NG2 immunostaining." (PMID 33346402, 2021). "T lymphocytes of stroke patients produced IFN-γ and TNF-α and responded to MBP peptides by increasing their production of TNF-α and IL-10 at admission, but not at later time points." (PMID 32719588, 2020). "Consistently, Western blotting showed that protein expression levels of MBP, oxytocin, and BDNF were significantly increased in the post-ischemic brain of hypothermia group compared to stroke control group." (PMID 32010477, 2020).
Stroke (continued). "During a stroke, BBB breakdown induces the leakage of oligodendrocyte antigens, such as myelin oligodendrocyte glycoprotein (MOG), and myelin basic protein (MBP) into the periphery." (PMID 32174916, 2020). "We observed a restoration of MBP and synaptophysin levels in the MCAo GDF11 group in the peri-infarct area and CC at 30 days after stroke." (PMID 32365331, 2020). "In a cohort of 28 patients with milder ischemic stroke, frequencies of MOG and MBP-specific IFN-γ responses, that were measured in peripheral blood, were increased early within the first week after stroke and decreased at 3 months." (PMID 31001280, 2019). "Whereas mucosal administration of MBP can induce a TGF-β-mediated Th2/Tregs response, contributing to a better neurological outcome for up to 1 month after stroke." (PMID 31133816, 2019). "Some autoantibodies to brain antigens (e.g., MBP, PLP, NF, and NR2A/2B) have been documented in individuals after stroke." (PMID 29422904, 2018). "Accordingly, the induction of MBP-induced or MOG-induced tolerance was found to prevent CNS autoimmunity and improve outcomes in experimental stroke." (PMID 29422904, 2018). "Secondarily, we demonstrated that linagliptin after stroke decreased the presence of peptides derived from NEUG and MBP." (PMID 29776406, 2018). "Protein markers of cerebral damage, including myelin basic protein (MBP), neuron-specific enolase (NSE), S100β, and glial fibrillary acidic protein (GFAP), are found in CSF and serum after stroke." (PMID 25309322, 2014). "In experimental stroke, systemic inflammation at the time of MCAO in rats induced the development of a deleterious autoimmune response to MBP after 1 month." (PMID 25309322, 2014). "Iba1 and myelin basic protein (MBP) staining indicated white matter lesions compared with non-lesional white matter in stroke patient 2 (80 years old)." (PMID 40221393, 2025). "While our previous study has preliminarily indicated the potential role of HDAC3-miKO in white matter injury by MBP/SMI32 immunostaining 30, further investigation is still needed to determine how exactly HDAC3-miKO exerts its role in post-stroke white matter, either protective or reparative." (PMID 39744685, 2025). "We then performed immunohistochemistry for CD36 and MBP, revealing that, although many MBP+ cells disappeared from the ischemic areas, MBP+ staining, which did not keep the original arrangement, was observed in ischemic areas even after stroke." (PMID 39451255, 2024). "In this study, at 7 and 21 d after stroke, both the nondiabetic and diabetic mice with stroke showed obvious myelin loss (LFB-positive staining and expression of MBP decreased) in peri-infarct areas, such as the corpus callosum and the striatum." (PMID 36615583, 2023). "Second, the level of LFB staining and the MBP expression were lower in the diabetic mice with stroke than in the nondiabetic mice with stroke, but with no significance." (PMID 36615583, 2023). "Our data also indicate that 3 μg/kg VT treatment in T1DM stroke rats significantly increases MBP(p < 0.001), decreases SMI‐32 (p < 0.01), and decreases SMI‐32/MBP ratio (p < 0.01) in the IBZ compared to PBS‐treated T1DM stroke rats." (PMID 33346402, 2021). "Both stroke and CORT disrupted MBP-positive structures within CST." (PMID 34206635, 2021). "Induction of a Treg response to MBP in Lewis rats before stroke resulted in an improved outcome at early, but not late (3 months) time points after stroke." (PMID 31281252, 2019). "This was confirmed by both IHC and western blot (P < 0.05) suggesting that MBP expression is reduced after isolation and this effect is independent of stroke." (PMID 27125783, 2016). "MBP expression was significantly higher in the PH group [ST-PH and SH-PH (sham mice paired with a stroke partner)] compared to SI mice [ST-ISO and SH-ISO (stroke and sham isolated mice)]." (PMID 27125783, 2016).
Stroke (continued). "Additionally, immune responses against MBP and GFAP were found to be more common in stroke patients with acquired infection and had worsened outcomes compared to stroke patients without infection." (PMID 26742037, 2016). "MBP-reactive T cells are evident in diverse neurological disorders such as MS, TBI, SCI and stroke." (PMID 26377390, 2015). "Furthermore, administration of mesenchymal stromal cells (MSCs) even at 7 days after stroke substantially increased NG2 positive OPCs in the SVZ and MBP positive oligodendrocytes in the peri-infarct striatum and corpus callosum 4 months after stroke." (PMID 24194700, 2013). "To investigate stroke‐induced changes in pan‐lactylation across different brain cell types, we performed immunofluorescence co‐staining of pan‐Kla with markers of neurons (MAP2 or NeuN), astrocytes (GFAP or S100β), microglia (IBA1), and oligodendrocytes (Olig2 or MBP)." (PMID 40271828, 2025). "The term “brain‐derived antigens” has been used in EAE and stroke research for many years, often represented by injury‐related proteins like myelin basic protein and oligodendrocyte glycoprotein, but it fails to encompass the diverse debris and molecules post‐TBI." (PMID 38468459, 2024). "It is reasonable to assume that a stroke affecting mainly white matter would give another pattern (e.g. high serum levels of MBP but not tau) than a stroke affecting mostly grey matter in cortex or basal ganglia (e.g. low serum levels of MBP but high levels of UCHL1 and tau)." (PMID 35765081, 2022). "Furthermore, stroke patients with acquired infection appeared to present immune responses against myelin basic protein and glial fibrillary acidic protein, and have worse outcomes compared to stroke patients with no infection." (PMID 27923376, 2016). "Studies about MBP reported that it is not a good plasma marker in first 6 hours of stroke." (PMID 26648996, 2015). "Additionally, immunostaining with MBP and SMI32 3 days after tMCAO showed that IL-13 did not reduce the demyelination damage caused by tMCAO during the acute phase of stroke, suggesting that IL-13 may promote white matter repair after tMCAO." (PMID 35578342, 2022). "The MBP levels have been confirmed to be correlated to the stroke severity at baseline, and higher values were predictive of a poor short-term prognosis; however, data regarding the direct relationship between the concentrations of MBP and the severity of the WMI remain lacking." (PMID 28890692, 2017). "However, in mouse models of stroke there was no significant change in MBP or HR post-CBD." (PMID 28286481, 2017). "A significant (p < 0.05) reduction in MBP intensity in the CC and striatum of CD13KO as compared to WT mice after stroke, reflecting increased demyelination in the absence of CD13." (PMID 37817190, 2023). "No statistical correlation was detected between serum MBP (p>0.05, r=-0.07) and IMA (p>0.05, r=0.25) levels and NIHSS scores of stroke cases." (PMID 26648996, 2015).
schizophrenia (44 papers, 2010 to 2025). A major psychotic disorder characterized by abnormalities in the perception or expression of reality. "Several of these proteins such as GDI-1, GFAP, and MBP have been implicated in pathology of schizophrenia and ASD via neuronal-glial interactions." (PMID 40779003, 2025). "Antipsychotic therapy also caused a significant decrease in MBP-hydrolyzing activity in patients with schizophrenia (p = 0.0002), and associations of catalytic activity with interleukins were observed." (PMID 37189796, 2023). "Previously, we demonstrated the presence of antibodies to myelin basic protein endowed with proteolytic properties in patients with schizophrenia, and the association of this activity with the clinical features of the disease." (PMID 37189796, 2023). "Microarray studies of schizophrenia and bipolar disorder have frequently implicated myelin-related genes including MBP, and MOG." (PMID 22675524, 2012). "Such catalytic anti-MBP Abs can be associated with impaired myelination in schizophrenia." (PMID 32751323, 2020). "Furthermore, abnormalities in genes that code for Golli-MBP are linked with significant risk for schizophrenia." (PMID 25964736, 2015). "In psychiatric disorders such as schizophrenia and attention deficit hyperactivity disorder, WM impairment is reported, and in this context, our data showing an overexpression of MBP in CLA are quite interesting." (PMID 37095366, 2023). "Values of proteolytic activity of IgG to MBP in patients with schizophrenia and healthy volunteers (control)." (PMID 37431466, 2023). "For further analysis, fourteen IgG samples were selected including eight samples from schizophrenia patients with proteolytic activity to MBP and six samples from healthy individuals with negligible or “null” proteolytic activity." (PMID 37431466, 2023). "In our work, for the first time, we revealed the relationship between the MBP-hydrolyzing IgG activity level and the level of serum cytokines in schizophrenia patients." (PMID 37189796, 2023). "In patients with schizophrenia, catalytic antibodies (abzymes) hydrolyzing DNA, RNA, and miRNA, histones, and myelin basic protein (MBP) have been previously found." (PMID 37189796, 2023). "We found, for the first time, that the MBP-hydrolyzing activity of IgGs decreases during short-term antipsychotic therapy in patients with schizophrenia." (PMID 37189796, 2023). "The low substrate affinity and levels of proteolytic activity indicate that IgG-dependent hydrolysis of MBP is less effective in bipolar disorder compared to in schizophrenia." (PMID 35806400, 2022). "In previously published studies, we have already presented evidence of the presence of MBP-hydrolyzing antibodies in patients with schizophrenia and their heterogeneity." (PMID 35806400, 2022). "Our study of the proteolytic activity of antibodies revealed a significant (p < 0.0001) decrease in the MBP-hydrolyzing activity of IgG in bipolar affective disorder, compared to in schizophrenia." (PMID 35806400, 2022). "This is a notable difference in MBP-hydrolyzing antibodies in BD from schizophrenia, in which both proteolytic activity and hypomyelination of the cortical and white matter of the brain increase with the duration of the disease." (PMID 35806400, 2022). "An increased level of natural antibodies with catalytic activity hydrolyzing DAMPs (nucleic acids, histones, MBP) was found in schizophrenia." (PMID 35546942, 2022). "According to our previous data, the MBP-hydrolyzing activity of IgG in schizophrenia is increased in a pH range between 6 and 8.5, with an optimum at pH 7.5, and at acidic pH values, the activity is reduced." (PMID 35806400, 2022). "We also investigated markers of inflammatory response (C-reactive protein, IL-2, IL-6, IL-10), the activity of leukocytic elastase (LE) and α1-proteinase inhibitor (a1-PI), antibodies to S100B and myelin basic protein (MBP) in schizophrenia." (PMID 34025476, 2021).
schizophrenia (continued). "The blood of patients with schizophrenia also contains antibodies-abzymes with DNase, protease (hydrolysis of MBP and five histones), and amylase activities." (PMID 33802122, 2021). "We found that IgGs isolated and purified from sera of schizophrenia patients' blood hydrolyses human MBP, and the level of this hydrolysis significantly exceeds that of healthy individuals." (PMID 32851101, 2020). "When comparing the specific activity in patients with different types of disease course, we have found that patients with a continuous course of paranoid schizophrenia (1.810 [0.746; 4.101 mg MBP/mg IgG/h]) had maximal activity values." (PMID 32851101, 2020). "The level hydrolysis of myelin basic protein (MBP) by IgG in patients with schizophrenia was studied depending on the clinical features and course of the disease." (PMID 32851101, 2020). "Recently, we detected catalytic antibodies in serum of patients with schizophrenia that hydrolyze MBP." (PMID 33008051, 2020). "Our results demonstrate that IgGs from schizophrenia patients catalyze the hydrolysis of MBP, and this activity is significantly higher than IgGs from control subjects." (PMID 32851101, 2020). "An increase in the level of antibodies to neuroantigens, including MBP-antibodies, in schizophrenia correlates with the severity of clinical symptoms." (PMID 32851101, 2020). "The peak signal in the 16th ranked region is closest to MBP, a major constituent of the myelin sheath of oligodendrocytes and Schwann cells, and shown to be involved in schizophrenia." (PMID 26943675, 2016). "In schizophrenia, there is reduced MBP mRNA in human visual cortex, as well as other cortical areas, suggesting that MBP expression in visual cortex is vulnerable to neuropsychiatric disease." (PMID 25964736, 2015). "Quetiapine ameliorated the schizophrenia-like behaviors and decreased expression of myelin basic protein and inhibition of Notch signaling molecules, such as Notch1, Hes1, and Hes5, in the forebrain that induced by cuprizone." (PMID 26232790, 2015). "Post hoc testing showed that MBP mRNA in schizophrenia was reduced compared to major depression (Šidák P = 0.003) but not to bipolar disorder (Šidák P = 0.195)." (PMID 22675524, 2012). "MBP expression was reduced in schizophrenia (ANOVA P = 0.004; planned contrast schizophrenia<controls, P = 0.006)." (PMID 22675524, 2012). "Reduced MBP mRNA in schizophrenia replicates findings in other brain regions and is consistent with oligodendrocyte involvement in the disorder." (PMID 22675524, 2012). "Thus, some proteolytic abzymes exhibit properties of acid proteases, such as MBP-hydrolyzing IgG in MS or histone-hydrolyzing IgG in schizophrenia." (PMID 35806400, 2022). "A comparison of the level of MBP-hydrolyzing activity in autoimmune and mental disorders showed that the percentage of antibodies with pronounced activity decreases in the following series: MS (84%) < schizophrenia (69%) < BAR (52%)." (PMID 35806400, 2022). "There are consistent reports of reduced expression of genes (MAG, MAL, MBP, PLP, MOG, NRG1, and Olig2, among others) associated with oligodendrocytes and myelin, and therefore involved in neuronal development or signal transmission in schizophrenia." (PMID 35326310, 2022). "We also showed earlier pronounced differences in the level of MBP-hydrolyzing activity of serum antibodies depending on the clinical features of schizophrenia, such as the type of course of the disease, the duration of the disease, and the presence of remission." (PMID 35806400, 2022). "Thus, there is significant heterogeneity in both the individual level of activity of MBP-hydrolyzing antibodies and the spectrum of activity in bipolar disorder and schizophrenia." (PMID 35806400, 2022). "We demonstrated that the serum activity of LE and a1-PI, and antibodies to the protein S100B and MBP may be related to the diagnosis of schizophrenia, which confirms the data obtained earlier by us." (PMID 34025476, 2021).